LINC02381 (long independently transcribed non-coding RNA 2381)
Synonyms: LOC400043; HMS; lncEPAT
Gene: Long non-coding RNA gene on chromosome 12 (54,126,019 to 54,147,485, forward strand). Ensembl gene ENSG00000250742.
Diseases named in the same sentence as LINC02381 in open-access papers:
LINC02381 is named in the same sentence as 9 diseases in open-access papers, as found by Europe PMC text mining. Sharing a sentence is not in itself a finding about the gene and the disease. The quoted sentences say what the papers report.
breast carcinoma (2 papers, 2022). "In addition, LINC02381 is persistently expressed at low levels in breast cancer tissues, which might be related to immunity." (PMID 35928921, 2022).
colon cancer (1 paper, 2020). "The survival analysis showed that a high expression of AC008760.1, AC009237.14, AC083809.1, AL391422.4, AL445645.1, LINC01063, LINC01234, and LINC02381 was associated with a poor prognosis in colon cancer." (PMID 32425969, 2020). "The expression of AC008760.1 was significantly correlated with the depth of colon cancer invasion, and the expression of AC008760.1, AL445645.1, AC009237.14, AL391422.4, and LINC02381 was significantly associated with lymph node metastasis." (PMID 32425969, 2020). "In addition, we finally tested the expression of LINC02381 in cell lines and found that LINC02381 was highly expressed in colon cancer cell lines." (PMID 32425969, 2020).
endometriosis (1 paper, 2022). The growth of functional endometrial tissue in anatomic sites outside the uterine body. "Upon further screening and verification of the differentially expressed lncRNAs by whole-transcriptome sequencing and qRT-PCR, LINC02381 was herein identified as a potentially relevant regulatory factor in endometriosis." (PMID 35327987, 2022). "On the other hand, simultaneous inhibition of miR-27b-3p and LINC02381 induced the expression of CTNNB1, which in turn, enhanced the proliferation of ESCs, suggesting that the LINC02381/miR-27b-3p/CTNNB1 axis is a potential prognostic biomarker and therapeutic target for endometriosis." (PMID 35327987, 2022).
rheumatoid arthritis (1 paper, 2023). A chronic, systemic autoimmune disorder characterized by inflammation in the synovial membranes and articular surfaces. "In addition, LINC02381 was significantly upregulated in chronic autoimmune inflammatory diseases, accelerating rheumatoid arthritis development." (PMID 36988257, 2023).
tumor (3 papers, 2020 to 2022). "For instance, HCG18, PVT1, and LINC02381 are highly expressed in BC and expedite tumor progression." (PMID 37304675, 2021). "For example, some lncRNAs, such as NOC2L-4.1, TUG1, and MALAT1, are well established to promote tumour growth, while other lncRNAs, such as ASMTL-AS1, LINC02381, and LINC02499 have been found to inhibit tumour progression." (PMID 33243205, 2020).
cancer (2 papers, 2021 to 2022). A tumor composed of atypical neoplastic, often pleomorphic cells that invade other tissues. "Among the 11 autophagy-related lncRNAs, 8 lncRNAs were already verified to be associated with cancer development: LINC01063, CD27-AS1, LINC00957, EIF3J-DT, LINC02474, SNHG16, LINC02381, and LINC01011." (PMID 36035142, 2022). "Considering that the role of LINC02381 in cancer remains disputed, we suggest that LINC02381 may work together with other genes in regulating ferroptosis." (PMID 35154072, 2021). "LINC02381 is an oncogene that has been validated by many cancer researchers." (PMID 35154072, 2021).
LINC02381 also shares sentences with these, for which no sentence is quoted: glioblastoma (2 papers); colorectal carcinoma (1); lymph node metastasis (1).